TNF (tumor necrosis factor)
Diseases named in the same sentence as TNF in open-access papers (continued):
Sharing a sentence is not in itself a finding about the gene and the disease.
psoriasis (continued). "In the last few decades, psoriasis treatment has significantly progressed with the identification of multiple new therapeutic targets and the introduction of biological therapies such as tumor necrosis factor-alpha (TNF-α), interleukin (IL)-12/23, and IL-17 inhibitors." (PMID 33883587, 2021). "Interestingly, in nontransformed colonocytes, inflammatory cytokines (e.g., TNF-α) could induce strong ERBB4 expression through a mechanism involving NF-κB signaling, while both TNF-α and NF-κB play crucial roles in psoriasis pathogenesis." (PMID 34667159, 2021). "Additionally, TNF-α is also considered an important mediator in inflammatory skin disorders, including psoriasis, a popular chronic inflammatory ailment marked by aberrant keratinocyte proliferation, increased cutaneous vascularity, and numerous infiltrating inflammatory cells." (PMID 34679744, 2021). "In addition to keratinocytes, dermal fibroblasts, through interaction with immune cells and cytokines such as IL-17A and TNF in psoriasis, can be a major source of IL-19 and IL-24 that contribute to perpetuation of psoriatic symptoms such as keratinocyte proliferation and acanthosis." (PMID 34616394, 2021). "Hence, the inhibition of TNF-α- and IL-12-producing pro-inflammatory macrophage in psoriasis lesions through topical medication delivery may present a safe alternative therapy." (PMID 34572503, 2021). "Furthermore, both TNF-α and IL-6 can induce IL-24 production in psoriasis." (PMID 34638757, 2021). "Given the key role of the TNF-α/IL-23/IL-17A axis in the pathogenesis of psoriasis, it could be hypothesized that polycyclic aromatic hydrocarbons (PAHs), such as TCDD, via AHR activation have a potential impact on the development or aggravation of the disease." (PMID 33921372, 2021). "Furthermore, IL-36α may locally ameliorate the effects of IL-17α and TNF-α, and contributed to the pathomechanisms of psoriasis." (PMID 34675805, 2021). "Therefore, further studies may investigate furin expression in psoriasis and rheumatological patients prior to and after treatment start with TNF-α inhibitors." (PMID 33644099, 2021). "As epidermal hyperplasia and inflammation are hallmarks of psoriasis, our new findings indicate that alantolactone can not only alleviate these skin lesions by inhibiting inflammation but also relieve epidermal hyperplasia by reducing the expression of TNF-α, IL-6, IL-1β, IL-8, IL-17A, and IL-23." (PMID 34202301, 2021). "The pathogenesis of psoriasis seems to be driven by the interaction between innate immune cells, adaptive immune cells and keratinocytes, in a process mediated by cytokines (including interleukins (IL)-6, IL-17 and IL-22, interferon and tumor necrosis factor) and other signaling molecules." (PMID 32224981, 2020). "Although TNFα-targeting and IL-17a-targeting drugs have been found to be effective, a targeting strategy that inhibits Peli1 might be a more powerful approach to treat psoriasis." (PMID 32873845, 2020). "A shared TNF-α-mediated pathogenesis between psoriasis and sarcoidosis may exist." (PMID 32823524, 2020). "TNF-α antagonists might partly exert their effects on psoriasis via this pathway." (PMID 32280718, 2020). "Subcutaneous injection of IL‐23, together with IL‐12 and TNF produced by LCs and DCs, activates αβT and γδT cells to produce IL‐22 and IL‐17A/F, which stimulate keratinocyte proliferation, release S100 protein and β‐defensin, and promote the production of growth factors and chemokines in psoriasis." (PMID 32916775, 2020). "Therefore, anti-TNF-α agents may have the capacity to suppress Th1 response in Th1 driven diseases, such as psoriasis, and, otherwise, Th2 response in Th2 driven diseases, such as BP, depending on the levels of INF-γ." (PMID 33050407, 2020). "In addition to the high production of cytokines relevant to psoriasis, such as of IFN-γ and TNFα, pathogenic Th17 cells display several features that could contribute to the physiopathology of autoimmune diseases." (PMID 32801996, 2020).
psoriasis (continued). "However, looking on the effects of cytokines highly relevant in the pathogenesis of psoriasis, i.e., IL-17A, IL-17F, IL-1α, or TNF, on S100A8 or S100A9 expression in keratinocytes we found strong effects on mRNA induction for both genes most pronounced for IL-17A > IL-17F > IL-1α > TNF." (PMID 33643287, 2020). "Importantly, TNF-α, together with IL-17, induces IL-36γ in psoriasis lesions, which in turn promotes expression of AMP and chemokines recruiting neutrophils and Th17 cells, as well as interferes with terminal differentiation and cornification process of the epidermis." (PMID 32161545, 2020). "Therefore, lymphotoxins might be deeply involved in psoriasis pathogenesis, and TNF‐α could tightly control their expression in both keratinocytes and lymphocytes." (PMID 31577850, 2020). "Finally, the product of IFNγ and TNFα positively associated with early non-calcified coronary burden in patients with psoriasis (n = 224; β = 0.28, p < 0.001)." (PMID 32646751, 2020). "In addition, ICAM-1 was an important molecule to recruit immunocytes to the skin and contribute to psoriasis, which could be triggered by TNF-α in diverse cell types." (PMID 32515468, 2020). "According to the previous research and clinical experience, several cytokines are released from immune and inflammatory cells during psoriasis, such as TNF-α, IL-17A, and IL-226,14–17, which are speculated to act directly on human keratinocytes and cause a variety of pathological symptoms." (PMID 32076123, 2020). "These genes may encode for TNF super family, IL-1, IL-6, IL-8, iNOS, major histocompatibility complex class 1 (MHC class 1) antigens, E-selectin, and vascular cell adhesion molecule 1 (VCAM-1), which are mostly involved in psoriasis." (PMID 32848730, 2020). "In addition, TNF-α and LPS were used as stimuli to induce a psoriasis-like in vitro model." (PMID 32059361, 2020). "Concerning the unknown expression and role of lymphotoxins in paradoxical reactions and in classical psoriasis, a previous study confirmed the pivotal function of LT‐α, together with TNF‐α, in determining NF‐κB‐mediated skin inflammatory reactions in IκBα−/− mice." (PMID 31577850, 2020). "Importantly, some of their shared features are relevant to the drugs prescribed for these diseases: the monoclonal antibodies adalimumab and infliximab are antagonists of TNF, whose corresponding gene variation in a number of diseases including CD, UC and psoriasis." (PMID 30169824, 2019). "To better understand the molecular mechanisms of Anti-TNF- α therapy, we analysed the global gene expression profile (using mRNA microarray) in peripheral blood mononuclear cells (PBMCs) that were collected from 6 psoriasis patients before and 12 weeks after the treatment of etanercept." (PMID 30953507, 2019). "Psoriasis is currently regarded as an auto-immune disease because it shares many features with other autoimmune diseases such as chronicity of the clinical symptoms and chronic inflammation, involvement of TNF-α and a genetic background with overlapping gene loci with other auto-immune diseases." (PMID 31417571, 2019). "Psoriasis is a chronic inflammatory skin disease with an immune response steered by IL-23 and TNF-α producing antigen presenting cells, thereby stimulating T cells to produce IL-17, a cytokine that is now identified to be of chief importance for inducing skin inflammation in psoriasis." (PMID 31191513, 2019). "Further, IL-22 promotes the expression of proinflammatory cytokines including IL-1, TNF-α, and GM-CSF, all of which have been shown to be highly expressed in lesional skin following irritant exposure and are well known to be involved in the pathology of psoriasis." (PMID 31781680, 2019).
psoriasis (continued). "Furthermore, previous studies have demonstrated vascular regression, decreased growth factor expression, and reduced immune cell infiltration in the skin and synovium of psoriasis and PsA patients, respectively, in parallel with clinical improvement following anti-TNF-α therapy." (PMID 31864394, 2019). "Then, growth factors and relevant cytokines (IL-17A, TNF-α, and IL-1β) in psoriasis activate mTOR and promote keratinocyte hyperproliferation and inhibit differentiation, which might be the mechanism underlying the PI3K/Akt pathway and psoriasis." (PMID 31824416, 2019). "Psoriatic patients showed an increase in TNF-α expression, which could promote the activation of the death receptor-mediated pathway as verified by a significant increase of the expression of caspase-8 revealed for granulocytes in both forms of psoriasis." (PMID 30301214, 2018). "A recent study on human tissues showed that psoriasis and atherosclerosis exhibit significant overlap of their transcriptomes and in particular that TNF, IFNg, and IFNγ-induced genes, which are common between psoriasis and atherosclerosis may provide the link between the two diseases." (PMID 29971067, 2018). "Moreover, therapies targeting IL-1, IL-17 and TNF have shown promise in preclinical and clinical trials, implying that our analysis may provide insight into potential drug targets for psoriasis." (PMID 29871627, 2018). "Therefore, the use of a TNF-α antagonist may increase the expression of the skin barrier and ameliorate the symptoms of psoriasis by improving the barrier protein expression." (PMID 29679037, 2018). "In addition, lower dose of IL‐35 recombinant protein could achieve long‐term treatment effects as TNF‐α monoclonal antibody did in the psoriasis mouse." (PMID 29193791, 2018). "Anti-TNF therapy has resulted in major improvement not limited to patients with RA also for people that have other serious inflammatory diseases, such as Crohnʹs disease, ulcerative colitis, psoriasis, psoriatic arthritis, ankylosing spondylitis and juvenile RA." (PMID 29881431, 2018). "In addition, a number of studies have shown that treatment of psoriasis patients with TNF-α inhibitors leads to decreased risk of cardiovascular events compared to methotrexate, and greater risk reduction was found with longer duration of anti-TNF-α treatment." (PMID 29065479, 2017). "In part, this may also be favored by the treatment of psoriasis with corticosteroids or novel immunosuppressive agents such as tumor necrosis factor alpha (TNFα) or interleukin-17 (IL-17) inhibitors, as these pharmacological interventions specifically affect antifungal immune responses." (PMID 28590443, 2017). "Thus, TNF-α modulates the key pathway of the IL-23/Th17 axis in psoriasis." (PMID 29232931, 2017). "Therefore, body weight should be monitored in psoriasis patients treated with TNF-α inhibitors, and appropriate weight reduction measures may be required to reduce the cardiovascular risk." (PMID 29065479, 2017). "Furthermore, the proinflammatory cytokines involved in psoriasis pathogenesis—tumor necrosis factor (TNF) and interleukin (IL)-6—may also alter sleep physiology." (PMID 26745869, 2016). "In addition, they can serve as non-professional antigen presenting cells through up-regulation of antigen presenting molecules–MHC-I and MHC-II in certain inflammatory conditions, e.g., in psoriasis, likely in response to IFNγ or other inflammatory cytokines such as TNFα." (PMID 27467256, 2016). "This T helper subset, by producing pro-inflammatory cytokines such as IL-22 and tumor necrosis factor-α (TNF-α), is implicated in the pathogenesis of autoimmune disease including RA, SLE, Behçet’s disease, type 1 diabetes, immune thrombocytopenia, psoriasis and MS." (PMID 27651750, 2016).
psoriasis (continued). "Thus, we are prompted to hypothesize that this anti-TNF-α agent may be beneficial not only in terms of disease severity, but also in terms of bone quality in patients with moderate-to-severe psoriasis by reducing serum adiponectin levels." (PMID 27293954, 2016). "On the one hand, TNF-α is overexpressed in adipose tissue from obese animals and humans, while on the other hand its excessive production is evidenced in the skin or joints in psoriasis and psoriatic arthritis leading to the rapid growth of skin cells and/or damage to joint tissue." (PMID 27455297, 2016). "Interestingly, levels of S1P (and all of the sphingoid bases) were not decreased in severe psoriasis following treatment with Etanercept, suggesting that circulating S1P is associated with severe disease pathology independent of the TNF-α pathway." (PMID 26174087, 2015). "Psoriasis lesions develop as a consequence of abnormal keratinocyte (KC) proliferation, which may be driven by key pro-inflammatory cytokines, including tumor necrosis factor (TNF), interleukin (IL)-17A and IL-23." (PMID 26251673, 2015). "In fact, in a mouse model of imiquimod-induced psoriasis-like inflammation, topical curcumin was demonstrated to improve the skin lesions with an effect comparable to that of clobetasol and to significantly decrease the cutaneous levels of IL-17A, IL-17F, IL-22, IL-1β, IL-6, and TNF-α mRNA." (PMID 26090395, 2015). "Notably, one of the common side effects of TNF-α therapy is psoriasis and data from mouse models suggest this may be due to an anti-TNF-α-mediated decrease in Treg frequency in the skin." (PMID 25741338, 2015). "In particular, a pathogenic excess of IFNα/β in SLE, SS, dermatomyositis and early stages of psoriasis, along with an excess of TNFα in RA, inflammatory bowel disease, Crohn’s disease and psoriasis, may induce the generation of detrimental monocyte-derived inflammatory DCs." (PMID 25889583, 2015). "In the past decade, Th1 cytokines such as interferon-γ (IFN-γ) and tumor necrosis factor-α (TNF-α) were considered to play a major role in this disease, but recent evidence points toward a central role of IL-23 and IL-17A in the physiopathogenesis of psoriasis." (PMID 26351408, 2015). "Current evidence suggests that psoriasis is an immune-mediated disorder and novel therapies involved in the suppression of the immune responses, such as the T cell-targeted agents and tumor necrosis factor (TNF) inhibitors, have improved the outcome of the disease." (PMID 24005976, 2014). "A case-control study was performed to assess the serum levels of TNF-α, IL-12/23p40, and IL-17 in patients with plaque psoriasis, compare them with healthy controls, and correlate them with disease severity, as represented by Psoriasis Area Severity Index (PASI)." (PMID 25759829, 2014). "In addition, psoriasis is characterized by local and systemic increases in levels of proinflammatory cytokines, such as interleukin-6 (IL-6) and tumor necrosis factor-alpha (TNF-α)." (PMID 25587268, 2014). "Tumor necrosis factor-α (TNF-α) may play an important role in the recalcitrant inflammatory and hyperproliferative dermatosis of psoriasis, and there may be a relationship between TNF-α polymorphisms and psoriasis risk." (PMID 24324571, 2013). "In addition, blockade of IL-23 signaling using a monoclonal antibody (ustekinumab) against the p40 subunit of IL-12 and IL-23 has been shown to be effective in Crohn's disease, psoriasis and psoriatic arthritis with results similar to those seen when blocking IL-6 or TNFα." (PMID 22229105, 2012). "Furthermore, it was reported that the development of ANA and anti-ds-DNA Abs in anti-TNF therapies may act as a marker of forthcoming treatment failure in patients with psoriasis." (PMID 22192852, 2011). "However, given the roles played by TNFα we hypothesized in recent work that targeting of TNFα mRNA by local RNAi in the skin would serve as a potential strategy towards treatment of psoriasis." (PMID 20594301, 2010).
psoriasis (continued). "Psoriasis and related Th17-driven dermatoses frequently co-occur with NAFLD and other hepatic conditions, reflecting shared systemic inflammation (IL-17/IL-23/TNF-α axes)." (PMID 41601665, 2026). "This is the first study to compare the therapeutic potential of intact and cytokine-preconditioned (IL-17, IL-22, and TNF-α) hUCB-MSCs and hUCB-MSC-Exo in a mouse model of IMQ-induced psoriasis-like skin inflammation." (PMID 40906403, 2025). "In dermatology, monoclonal antibodies targeting tumor necrosis factor alpha (TNF-α) and specific interleukins (ILs) are particularly effective in the treatment of psoriasis, given the central role of the IL-23/Th17 axis in the disease’s pathogenesis." (PMID 41302127, 2025). "Here, we spiked whole blood with infliximab, a well characterized anti-tumor necrosis factor α (TNF-α) chimeric antibody used to treat autoimmune diseases including inflammatory bowel disease, arthritis, ankylosing spondylitis, and psoriasis." (PMID 39882960, 2025). "Pathway enrichment confirmed the involvement of IL-17 and TNF signaling, PPAR signaling, arachidonic acid metabolism, and nitrogen metabolism, pathways well-established in psoriasis and increasingly recognized in AD pathogenesis." (PMID 41465136, 2025). "Tumor necrosis factor-α (TNF-α), a key cytokine in the pathogenesis of psoriasis, impairs insulin signaling by inhibiting the tyrosine kinase activity of the insulin receptor and reducing adiponectin secretion." (PMID 40806666, 2025). "Numerous studies have demonstrated that the serum levels of TNF-α, IFN-γ, IL-6, IL-8, IL-12, IL-18, and IL-30 are significantly elevated in patients with active psoriasis compared to healthy individuals." (PMID 40731810, 2025). "In a murine psoriasis model, TLR2 signaling contributed significantly to the itching by mediating the expression of CXCL1/2, IL-31, IL-33, ST2, IL-6, and TNF-α." (PMID 40995100, 2025). "Pro-inflammatory mediators, including tumor necrosis factor-alpha (TNF-α), interleukin (IL)-17, and IL-23, play pivotal roles in the pathogenesis of psoriasis." (PMID 40243475, 2025). "At the same time, psoriasis patients produce a significant amount of inflammatory factors, such as IFN−γ (interferon γ), IL-22 (interleukin-22), TNF−α (tumor necrosis factor α) and IL−1β (interleukin-1β)." (PMID 40385577, 2025). "ASO-210-loaded UCMSC-exosomes reduced psoriasis symptoms, exhausted Th17 cells and reduced enrichment of proinflammatory cytokines, such as IL-17A, IFN-γ, IL-6 and TNF-α, in both spleen and skin lesions in vivo." (PMID 39861699, 2025). "In psoriasis, PRP alleviates keratinocyte hyperproliferation and plaque inflammation by inhibiting IL-17 and TNF-α." (PMID 41246327, 2025). "CD8+ T cells are central to psoriasis, producing pro-inflammatory cytokines such as IFN-γ and TNF-α." (PMID 40694426, 2025). "Proteins related to the central disease‐driving pathways of psoriasis, namely the TH1 (CCL3, CCL4, CXCL9, CXCL10, CXCL11, TNFα) and TH17 pathway (CXCL1, CCL20, IL‐17A, IL‐12B) were found elevated in lesional skin across both studies." (PMID 40970551, 2025). "MSC exosomes also suppressed DC maturation and activation and inhibited the release of pro-inflammatory cytokines (TNF-α, IFN-γ, IL-1β), chemokines (CCL20 and CXCL8), and psoriasis-specific cytokines (IL-23)." (PMID 41007656, 2025). "From an immunologic standpoint, both LP and psoriasis are Th1- and Th17-driven diseases, characterized by elevated IFN-γ, TNF-α, and IL-17 activity." (PMID 40870891, 2025). "Myr was predicted to interact with TNF, PTGS2, and MMP9—targets well documented to contribute to lesion persistence, extracellular matrix remodeling, and inflammatory amplification in psoriasis." (PMID 41471291, 2025). "KEGG analysis indicated that shared genes participate in key inflammatory and immune pathways, including the IL-17, NF-kappaB, and TNF signaling pathways in IBD and psoriasis." (PMID 40093802, 2025).